U8 (U8 small nucleolar RNA )
Gene: Small nucleolar RNA gene on chromosome 6 (154,905,076 to 154,905,206, reverse strand). Ensembl gene ENSG00000238963.
Homologues: Orthologues: rabbit U8 (33% identical). Paralogues in human: U8 (56% identical), U8 (55% identical), U8 (54% identical), U8 (53% identical), U8 (52% identical), U8 (50% identical), U8 (49% identical), U8 (48% identical), U8 (47% identical), U8 (46% identical), U8 (45% identical), U8 (44% identical), and 1 more.